CDH1 (cadherin 1)
Diseases named in the same sentence as CDH1 in open-access papers (continued):
Sharing a sentence is not in itself a finding about the gene and the disease.
gastric cancer (continued). "In a collaborative study based on 11 CDH1 families, the International Gastric Cancer Linkage Consortium showed that the clinical penetrance for diffuse gastric cancer was high, as the estimated risk for carriers of developing the disease was 67 to 83%." (PMID 25848941, 2015). "The E-cadherin gene (CDH1) was found to be frequently mutated in diffuse type of gastric tumor, implying that E-cadherin inactivation is important for gastric cancer development." (PMID 25605238, 2015). "CDH1 and RARβ promoter hypermethylation was more frequently observed in the diffuse scattered type of gastric cancer." (PMID 25997695, 2015). "The same authors also observed that all families with CDH1 deletions originated from countries with low gastric cancer incidence rates." (PMID 25180051, 2014). "Although CDH1 gene sequencing was not conducted to identify possible mutations, the immunohistochemical analysis revealed the involvement of CDH1 in the early development of gastric cancer in a Brazilian population." (PMID 25180051, 2014). "Following screening of a panel of 115 probands with non-CDH1 familial gastric cancer, an unrelated family from Portugal was added to our study." (PMID 25340522, 2014). "The most well established familial form of gastric cancer is hereditary diffuse gastric cancer (HDGC [MIM 137215]), where approximately 40% of cases are attributed to germline mutations in the E-cadherin encoding gene, CDH1." (PMID 25340522, 2014). "However, researchers in many studies have suggested that environmental factors, lifestyles and ethnic differences might account for opposite directions in associations of the CDH1 − 160C → A polymorphism with gastric cancer among some Asian and Caucasian studies." (PMID 24684952, 2014). "Of these genes, promoter hypermethylation of CDH1 and MGMT was associated with worse outcomes after surgery for gastric cancer." (PMID 23179365, 2013). "Scientific societies insist on the need for prospective studies to establish the place of laparoscopy for gastric cancer (prophylactic gastrectomy for CDH-1 related gastric cancer, <T3 tumours, palliative gastrectomy)." (PMID 24759817, 2013). "In human gastric cancer, loss of expression of the CDH1 gene encoding for E-cadherin has frequently been detected, often due to promoter hypermethylation, particularly in diffuse-type lesions." (PMID 24216700, 2013). "From these findings, CDH1 methylation seems to take little part in the development of gastric cancer." (PMID 23280118, 2013). "The difference between the 2 distinct gastric carcinomas can be explained by the involvement of other genes in VEGF and CDH1 regulation or by different types of CDH1 mutations." (PMID 23437057, 2013). "Furthermore, since the germline CDH1 mutations have been found in only a certain percentage of familial gastric cancers, it is reasonable to hypothesize that CDH1 inactivation due to a previously unknown mechanism or inactivation of another gene plays a role in predisposing to gastric cancer." (PMID 19671196, 2009). "Therefore, persons with family history of gastric cancer are recommended for not only the OES, but also the screening for Helicobacter pylori infection and CDH1 mutation." (PMID 41517275, 2025). "Taken together, these data suggest that there is no peak age at which gastric cancer affects families with CDH1 variants." (PMID 39760880, 2025). "The identification of CDH1 mutations is crucial, as it directly influences management strategies, including the consideration of PTG, which is the most effective method to reduce the risk of developing gastric cancer in mutation carriers." (PMID 40585607, 2025). "The CDH1 PV was detected in the 29-year-old after her diagnosis of breast and gastric cancer." (PMID 40323501, 2025).
gastric cancer (continued). "We report no cancer deaths and no cases of advanced gastric cancer in AYA who underwent active surveillance instead of PTG for management of germline CDH1 P/LP variants." (PMID 39760880, 2025). "In gastric cancer cell lines, hyperglycemia induces endogenous fructose formation by increasing the flux of the polyol pathway, which in turn activates the KHK-A signaling pathway and inhibits CDH1 expression, thus inducing epithelial mesenchymal transition and promoting gastric cancer metastasis." (PMID 40549205, 2025). "Familial non-hereditary gastric cancer (FNHGC) serves as an umbrella term for families with two or more cases of gastric cancer in first- or second-degree relatives, but without identified CDH1, CTNNA1, or other high-penetrance germline mutations." (PMID 41097736, 2025). "Notably, we identified a PV in CDH1 gene in a patient with an early-onset lobular BC and a positive family history of breast and gastric cancers." (PMID 40361347, 2025). "CDH1 abnormalities and PJS are known genetic risk factors for early-onset gastric cancer." (PMID 38672634, 2024). "This is evident in hereditary gastric cancer, where mutations in the CDH1 gene result in the absence of E-cadherin, ultimately leading to gastric cancer." (PMID 38660133, 2024). "In addition, gastric cancer samples from 14 patients (25%) presented with a transcriptomic profile (low levels of CDH1; high levels of ZEB1) consistent with the presence of an EMT (Epithelial-to-Mesenchymal-Transition) phenotype." (PMID 39323992, 2024). "CDH1 is a suppressor gene of gastric cancer, Although the variation in CTNNA1 was not initially noticed since it did not induce carcinogenesis 49, further studies have shown that CTNNA1 is indeed a susceptibility gene for gastric cancer." (PMID 36741258, 2023). "Of note, in contrast to the germline CDH1 mutations seen in diffuse hereditary gastric cancers and a subset of lobular breast cancer, no germline CDH1 mutations were identified in plasmacytoid UC." (PMID 37240925, 2023). "Since mutation or transcriptional silencing of the CDH1 gene is associated with gastric cancer, we also screened for the presence/absence of the mutation in this particular gene." (PMID 36831145, 2023). "Patients with CDH1-mutant gastric cancers generally carry a particularly poor prognosis." (PMID 35499650, 2023). "Indeed, Wnt signaling activations were also observed in two major predisposed causes of gastric cancer development, CDH1 mutation (encodes E-cadherin) and Helicobacter pylori infections." (PMID 37190019, 2023). "If 95% of CDH1 carriers have at least one signet ring cell carcinoma lesion in the total gastrectomy, and the cumulative risk of gastric cancer at 80 years old is 20 to 42%, more than half of CDH1 carriers with foci will not develop DGC." (PMID 37761816, 2023). "The hypermethylation of CDH1 has been demonstrated in gastric cancer." (PMID 36741258, 2023). "If there is a family history of DGC along with a PV in CDH1 or CTNNA1, then risk-reducing total gastrectomy should be considered, with preoperative endoscopy performed to identify whether gastric cancer has already developed." (PMID 37165697, 2023). "CDH1 and ARID1A identified in LP were commonly mutated in gastric cancer." (PMID 36703611, 2023). "Next-generation sequencing of unexplained young or familial gastric cancer cases without CDH1 mutations revealed that CTNNA1, MYD88, and MAP3K6 had deleterious mutations associated with gastric cancer." (PMID 36741258, 2023).
gastric cancer (continued). "CDH1-driven gastric cancers present as signet ring cell carcinoma (SRCC) and readily metastasize before forming large primary lesions, typically presenting at late stages upon detection (43% of SRCC are detected at a distant or metastatic stage vs. 37% for other gastric adenocarcinomas)." (PMID 37761816, 2023). "This is the case in young gastric cancer patients without CDH1 germline cancer causal mutations or other rare ones, such as those in the CTNN1A gene, that are supposed to strongly favor GC onset." (PMID 36551612, 2022). "Moreover, we reveal a possible molecular link showing that AKAP9 is a critical effector downstream of CDH1 in gastric cancer." (PMID 36317124, 2022). "CDH1 P/LP variants were identified in 141 patients, most commonly in patients with DGC (27/408, 6.6%) followed by colorectal signet-ring cell cancer (CSRCC; 3/79, 3.8%), gastric cancer (56/2756, 2%), and LBC (22/6809, 0.3%)." (PMID 34949788, 2022). "It was known that mutations in genes such as CDH1, PIK3CA, ARID1A (AT-rich interactive domain 1A), EGFR, and PTEN existed in gastric cancer, providing potential circulating DNA for detection of gastric cancer." (PMID 33693004, 2021). "However, we were interested in understanding if any HDACs were co-regulated with CDH1 in gastric cancer." (PMID 35008338, 2021). "Patient III.1 of gastric cancer family 2 with the heterozygous CDH1:c.1565 + 2dup p.?" (PMID 33929593, 2021). "The correlations also suggest that targeting Class IIa HDACs might provide greater specificity for gastric cancers with low CDH1 expression." (PMID 35008338, 2021). "In one case, the absence of a pathogenic/likely pathogenic CDH1 variant impacted gastric cancer screening recommendations for relatives." (PMID 33654310, 2021). "High levels of ZEB2 have previously been reported to promote epithelial-mesenchymal transition (EMT) of gastric cancer cells via regulation of expression of CDH1 (E-cadherin) and other EMT markers, such as VIM (vimentin) and matrix metallopeptidases (MMP2 and MMP9)." (PMID 33806113, 2021). "The patient with the CDH1 variant in this study did not present with lobular breast cancer, nor with a personal history or family history of gastric cancer, although there were 255 (3.2%) invasive lobular breast cancer patients in this study." (PMID 34606182, 2021). "Due to limited data, policies for genetic counseling and management in germline CDH1 mutation carriers in sporadic gastric cancer have not been established." (PMID 31892987, 2020). "While this may be a mechanism behind gastric cancer SRCC aggressiveness, CDH1 mutations are believed instead to contribute to earlier in tumor initiation." (PMID 32545410, 2020). "To date, studies have not evaluated known CDH1 missense mutations in a large number of unselected gastric cancer patients to determine the statistical association with clinical features." (PMID 31892987, 2020). "CDH1 was responsible for metastasis of gastric cancer and colorectal cancer." (PMID 30970615, 2019). "The isogenic gastric cancer and non-malignant breast cell line data provide valuable insights into possible targets for the chemoprevention and treatment of CDH1-deficient tumours." (PMID 30066183, 2019). "Our study was limited to explore the presence of germline variants only in the CDH1 gene and not in other gastric cancer predisposing genes." (PMID 30895400, 2019).
gastric cancer (continued). "Germline CDH1 was sequenced for 94 Māori gastric cancer patients and 200 healthy matched controls." (PMID 29589180, 2019). "We also found that mRNA expression levels of CDH1, CDKN1A, and EP300 were significantly reduced while those of RhoA, ROCK1, ROCK2, PIK3CA, and CCND1 were significantly increased in gastric cancers with reduced or loss of NKX6.3 expression compared to those in NKX6.3 positive cases." (PMID 30514953, 2018). "In addition, expression levels of CDH1, CDKN1A, and EP300 were reduced while expression levels of RhoA, ROCK1, ROCK2, PIK3CA, and CCND1 were increased in gastric cancer tissues with reduced or loss of NKX6.3 expression." (PMID 30514953, 2018). "Moreover, sporadic gastric carcinomas of diffuse type occurring in patients below the age of 45 years, so-called early onset gastric carcinomas, showed alteration in CDH1 gene." (PMID 30567376, 2018). "Earlier studies showed a lower prevalence of CDH1 germline mutations in patients with no history of gastric carcinoma." (PMID 30568591, 2018). "Similar to the MCF10A CDH1(−/−) mutant cells, c.1380delA CDH1 SB.mhdgc-1 gastric cancer cells showed altered gene expression of genes involved in cellular component organization, cytoskeletal organization, and cell adhesion, including microtubule nucleation involving genes like TUBB2." (PMID 28460635, 2017). "Together, this study integrates transcriptomic aberrations with drug cytotoxic responses in patient-derived c.del1380A CDH1 HDGC versus CDH1 wild type sporadic gastric cancer cells providing new therapeutic leads for the difficult to treat CDH1 mutant familial subtype of gastric cancer." (PMID 28460635, 2017). "In family 32, p.M1I in CDH1 and p.T1354M in BRCA2 are implicated in gastric cancer and BC respectively and knowing that the family presented with only BC, two hypothesis can be formulated." (PMID 28202063, 2017). "CDH1 is known to be associated with hereditary diffuse gastric cancer (HDGC) and other cancer types; however, none of the CDH1 variant carriers had history of gastric cancer." (PMID 29212164, 2017). "Furthermore, expression of a transcript of CDH1 (E-cadherin) intron 2 (CDH1a) has been shown to increase gastric cancer cell invasion and angiogenesis and this increase correlated with IFITM1 expression." (PMID 27186374, 2016). "Deep involvement of aberrant DNA methylation in human gastric cancers had been suggested by the fact that tumor-suppressor genes, such as CDH1, p16, and hMLH1, were inactivated more frequently by aberrant DNA methylation of their promoter CpG islands than by genetic alterations." (PMID 26823082, 2016). "In gastric cancer, a high TWIST protein expression level was associated with a reduction in CDH1 protein and with the increased CDH2 which may enhance cell motility in several cancer types." (PMID 27842518, 2016). "Cases of LCIS and ILC associated with CDH1 germline mutation without gastric cancer are also increasingly recognized." (PMID 25757734, 2015). "Germline mutations in CDH1 genes contribute to about 40% of hereditary diffuse gastric cancer (HDGC) cases, and Lynch syndrome families with inherited mutations in the mismatch repair genes are at an increased risk for gastric cancer." (PMID 26506520, 2015). "Methylation of CDH1 has been reported to be regulated by H. pylori infection in chronic gastritis and intestinal metaplasia patients, indicating that E-cadherin plays an important role in gastric cancer initiation." (PMID 25184143, 2014). "In China, this polymorphic variant of CDH1 has not achieved significant difference in its distribution between gastric cancer cases and controls." (PMID 24838934, 2014). "The identification of new germline mutations that appear to predispose individuals to familial gastric cancer can aid in identifying at risk individuals in affected families that are negative for CDH1 mutations." (PMID 25340522, 2014).
gastric cancer (continued). "Findings related to the influence of the −160C → A promoter polymorphism and haplotypes of the E-cadherin (CDH1) gene have not been consistent in previous studies regarding the risk for sporadic gastric cancer." (PMID 24684952, 2014). "Samples were from unrelated families that met international gastric cancer linkage consortium (IGCLC) criteria for hereditary diffuse gastric cancer, but had previously tested negative for mutation of the CDH1 locus, or familial intestinal gastric cancer." (PMID 25340522, 2014). "Based on direct sequencing analysis, our findings suggest that the CDH1 − 160C → A promoter polymorphism and haplotypes play significant roles in cancer risk for sporadic diffuse gastric cancer, but not for intestinal gastric cancer, in a Taiwanese population." (PMID 24684952, 2014). "CDH1 inactivation in gastric parietal cells does not induce gastric carcinoma, suggesting that loss of CDH1 is insufficient for tumor initiation." (PMID 25315765, 2014). "We have previously reported that CpG island methylation of both DAPK and CDH1, in non-neoplastic gastric mucosa, corresponded to an increased risk of gastric cancer." (PMID 23280118, 2013). "Methylated CDH1 in PPW predicts poor prognosis for gastric cancer patients." (PMID 22514028, 2012). "We have previously shown that certain CDH1 mutations have a negative influence on survival of gastric carcinoma patients and that CDH1 mutations are associated with enhanced EGFR activation." (PMID 22152101, 2011). "The present results suggest that germline mono-allelic hypermethylation of the CDH1 promoter is not a major predisposing factor for gastric cancer." (PMID 19671196, 2009). "Similarly, in cases of hereditary lobular breast cancer associated with a pathogenic CDH1 variant but without a family history of gastric cancer, endoscopic surveillance is advised annually." (PMID 41528496, 2026). "For instance, a study indicated that patients with chronic gastritis infected by H. pylori exhibited higher levels of CDH1 methylation, suggesting that H. pylori may act as a promoter of CDH1 gene methylation during the early stages of gastric cancer development." (PMID 40585607, 2025). "The predisposition is even stronger in carriers of CDH1 PVs, as this gene is linked to the Hereditary Diffuse Gastric Cancer (HDGC) syndrome, an autosomal dominant disorder characterized by a lifetime risk of advanced gastric cancer of approximately 10.3% in males and 6.5% in females." (PMID 40649708, 2025). "The most common hereditary GC is hereditary diffuse gastric cancer (HDGC), which is an autosomal dominant genetic syndrome often caused by E-cadherin gene (CDH1) mutation." (PMID 40291906, 2025). "A meta-analysis involving 6,399 subjects suggested that the CDH1–160 A allele might serve as a protective factor against gastric cancer in Asian populations (OR=0.67), but no such association was found in Caucasian populations." (PMID 40416864, 2025). "The identification of CDH1 mutations can occur through various genetic testing methods, including multigene panel testing, which has revealed pathogenic mutations even in individuals without a clear family history of gastric cancer." (PMID 40585607, 2025). "Pathogenic variants of CDH1 and CTNNA1 have been linked to gastric cancer (GC) and lobular breast cancer (LBC)." (PMID 40551901, 2025). "Moreover, the immune landscape in CDH1-related gastric cancer may differ from that in sporadic gastric cancers." (PMID 40585607, 2025). "SRC lesions are ubiquitous in CDH1 P/LP variant carriers, and yet lifetime advanced gastric cancer risk may be as low as 7%-10% in individuals with no family history of gastric cancer." (PMID 39760880, 2025). "Similarly, in gastric carcinoma, dual targeting of CDH1 and CDH2 suppressed migration and invasion." (PMID 40860670, 2025).